TP53INP1 (tumor protein p53 inducible nuclear protein 1)
Diseases named in the same sentence as TP53INP1 in open-access papers (continued):
Sharing a sentence is not in itself a finding about the gene and the disease.
pancreatic cancer (continued). "However, Fv1 efficiently kills pancreatic cancer cells by inducing a cell cycle arrest by the induction of cell cycle inhibitors involving TP53INP1." (PMID 26204945, 2015). "miR-155 is overexpressed in pancreatic cancer cells and interacts with TP53INP1 mRNA at its 3′UTR, whereas miR-125b is overexpressed in type II endometrial carcinoma cells and contributes to the malignancy of type II endometrial carcinoma, possibly through down-regulation of TP53INP1 expression." (PMID 23717325, 2013). "With respect to miRNAs which may regulate the expression of TP53INP1, several studies had reported that TP53INP1 was repressed by miR-155 in pancreatic cancer and miR-130b in hepatocelluar cancer, respectively." (PMID 21970405, 2011). "Indeed, it has been shown in recent studies that these miRNAs are involved in regulating development of pancreatic cancer via specific target genes (PDCD4, NF-kappaB, TP53INP1)." (PMID 25071021, 2014). "We found that silencing of TP53INP1, LATS2 and CD44 in MIA PaCa-2 cells significantly increased tumour growth compared with the vector control cells, indicating a bona fide tumour suppressor function in pancreatic cancer cells." (PMID 23857777, 2013). "Therefore, repression of TP53INP1, LATS2 and CD44 revealed that each gene plays an important role in controlling pancreatic cancer growth." (PMID 23857777, 2013). "In addition, this study provides a comprehensive mechanism for ZIP4-mediated pancreatic cancer growth involving CREB-dependent transcription, enhancement of oncogenic miR-373 expression, and reduction in key miR-373 regulated targets, including the tumour suppressor genes TP53INP1, LATS2 and CD44." (PMID 23857777, 2013).
hepatocellular carcinoma (21 papers, 2018 to 2024). A malignant tumor that arises from hepatocytes. "Additionally, loss of TP53INP1 has been found to promote metastasis in early-stage hepatocellular carcinoma cells through the DUSP10 phosphatase-mediated activation of the ERK pathway." (PMID 38436783, 2024). "Previous studies have shown that miR-543 acts in cardiac fibrosis, renal fibrosis, and endometrial fibrosis, and miR-1323 promotes tumor progression by targeting TP53INP1 in hepatocellular carcinoma." (PMID 37389959, 2023). "TP53INP1 siRNA diminished the discrepancy of expression of T-ICs markers, self-renewal ability, and tumorigenesis capacity between miR-96 knockdown hepatoma cells and control cells." (PMID 33046975, 2020). "Downregulation of TP53INP1 has been reported to promote hepatocellular carcinoma cell metastasis through the p73/DUSP10 pathway and activation of ERK1/2." (PMID 32448269, 2020). "Previous studies have revealed that the downregulation of TP53INP1 could activate a p73-dependent DUSP10/ERK signaling pathway to promote the metastasis of hepatocellular carcinoma." (PMID 32477928, 2020). "Moreover, downregulated TP53INP1 promoted hepatocellular carcinoma cell metastasis through the p73/DUSP10 pathway and activation of ERK1/2." (PMID 32448269, 2020). "MiR-182-5p expression is up-regulated in hepatocellular carcinoma, and the miRNA has been shown to function as an oncogene by targeting various genes, including SESN2 and TP53INP1, related to cancer." (PMID 29662624, 2018). "Moreover, lncRNA GAS5 could promote tumor progression by targeting TP53INP1 in hepatocellular carcinoma and the GAS5/TP53INP1 axis was also identified as gain interaction in our LIHC DysCeNet." (PMID 34222227, 2021).
gastric cancer (17 papers, 2011 to 2025). A primary or metastatic malignant neoplasm involving the stomach. "Besides, it had been reported that TP53INP1-positive rate decreased with the progression of gastric cancer; and TP53INP1 protein negativity was significantly associated with aggressive pathological phenotypes of gastric cancer." (PMID 24152184, 2013). "Besides TP53INP1 protein negativity was significantly associated with aggressive pathological phenotypes of gastric cancer; and TP53INP1-positive rate decreased with the progression of gastric cancer." (PMID 21970405, 2011). "PCAT18 can upregulate TP53INP1 expression to inhibit metastasis of gastric cancer by sponging miR-301a." (PMID 34787047, 2021). "Of interest, reduction of TP53INP1 expression in gastric cancer was closely correlated with their aggressive phenotypes." (PMID 26388699, 2015). "The expression of TP53INP1 was reduced in various human cancers, e.g., breast, pancreas and gastric cancers." (PMID 26388699, 2015). "And exosomal miR-155-5p-5p could also enhance proliferation and migration capabilities of cancer cells by inhibiting TP53INP1 expression in gastric cancer." (PMID 35070952, 2021). "It was found that miR-155-5p could promote epithelial-to-mesenchymal transition (EMT) through regulating TP53INP1 in paclitaxel-resistant gastric cancer cells." (PMID 35070952, 2021).
colorectal cancer (14 papers, 2014 to 2025). A primary or metastatic malignant neoplasm that affects the colon or rectum. "In colorectal cancer, miR-96 seems to contribute to cell growth, and target directly TP53INP1, FOXO1 and FOXO3a53." (PMID 38636197, 2024). "Our study showed that lncRNA TCONS_00026334 acts as an anti‐tumor and anti‐metastatic gene by regulating the miR548n/TP53INP1 axis in the development of colorectal cancer." (PMID 32986920, 2020). "TPGS mixed micelles with FA may cure colorectal cancer by targeting miRNA-221/TP53INP1 axis-mediated autophagy." (PMID 40325268, 2025). "For example, it was reported that miR-3934 is up-regulated in colorectal cancer cells and that down-regulation of miR-3934-5p may enhance the sensitivity of A549 non-small cell lung cancer cells to cisplatin by targeting TP53INP1." (PMID 35927714, 2022). "claimed that let-7f-5p promotes 5-FU resistance and it could directly repress several pro-apoptotic proteins including TP53INP1 in colorectal cancer, indicating that TP53INP1 might negatively regulate 5-FU resistance." (PMID 35070952, 2021). "Thus, FA-loaded TPGS mixed micelles could be a potential therapeutic agent for colorectal cancer by targeting miRNA-221/TP53INP1 axis-mediated autophagy." (PMID 38267567, 2024). "We evaluated the cell viability using MTT assay, flow cytometry, and the expression of Bax, CASP-3, TP53INP1 and miRNA-221 by RT-qPCR, in order to elucidate the mechanism of TPGS mixed micelles formula and ferulic acid in Caco-2 human colorectal cancer cell line." (PMID 38267567, 2024).
lung carcinoma (13 papers, 2015 to 2026). "MIR155HG induces proliferation, migration, and invasion in lung carcinoma by downregulating TP53INP1 via miR-155." (PMID 38339237, 2024). "Our results suggest that miR-19a participates in the progression of lung cancer through TP53INP1 downregulation." (PMID 26367773, 2015). "Moreover, the upregulation of miR-205-5p has been shown to contribute to lung cancer cell proliferation and metastasis by regulating TP53INP1, RB1, and P21." (PMID 39451748, 2024). "A previous study has revealed that 25 SNPs in the stem cell-related genes are significantly associated with the development of lung cancer the dominant genes include RAN rs14035, TP53INP1 rs7760, TP53INP1 rs896849, EPCAM rs1126497, HEY1 rs1046472, HEY2 rs3734637, OCT4 rs13409, and WNT2 rs3729629." (PMID 37563730, 2023). "It indicates that autophagy might play an important role in miR-106a/TP53INP1 regulation of BM in lung cancer." (PMID 34718338, 2021). "In addition, miR-106a/TP53INP1-regulated EMT demonstrated another mechanism promoting BM of lung cancer." (PMID 34718338, 2021). "To examine if over-expression of miR-182-5p could also regulate SESN2 and TP53INP1 in different cell type, we introduced a tetracycline-inducible (tet-on) miR-182-5p expression system to H1299 lung cancer cells to express miR-182-5p." (PMID 29662624, 2018). "Moreover, overexpression of miR-106a decreased TP53INP1 protein levels in lung cancer cells." (PMID 34718338, 2021). "Our results revealed that miR-19a downregulates the target genes FOXP1, TP53INP1, TNFAIP3, and TUSC2 and that these genes might play important roles in the tumorigenesis of lung cancer; however, the invasion inhibition potency was found to differ among the four genes." (PMID 26367773, 2015).
cervical cancer (8 papers, 2012 to 2025). A primary or metastatic malignant neoplasm involving the cervix. "miR- 155 - 5p regulated TP53INP1 expression in cervical cancer cells and was expressed at significantly high levels in cancer tissues, while downregulated miR- 155 - 5p expression suppressed tumor growth and metastasis." (PMID 40214727, 2025). "It has been reported that miR-17-5p inhibits cell growth and promotes apoptosis of cervical cancer cells by targeting TP53INP1." (PMID 35241117, 2022). "The down-regulation of microRNA-15a-5p represses cervical cancer progression through targeting TP53INP1." (PMID 33526036, 2021). "Previously, it was reported that knockdown of TP53inp1 suppressed the growth of cervical cancer cells and promoted apoptosis in Hela cells." (PMID 26512655, 2015). "In addition, miR-17-5p and miR-20a alleviate the suppressive function of myeloid-derived suppressor cells by modulating STAT3 expression, and miR-17-5p functions as a tumor suppressor by targeting TP53INP1 in cervical cancer cells." (PMID 27765929, 2016). "Notably, TP53INP1 was shown to be over-expressed in cervical cancer compared to normal tissue." (PMID 25192291, 2014).
prostate carcinoma (8 papers, 2013 to 2022). A carcinoma that arises from epithelial cells of the prostate gland. "MIR205 diminishes the radio-resistance of prostate cancer cells via downregulating TP53INP1, inhibiting autophagy and causing a subsequent impairment in viability and survival." (PMID 35317831, 2022). "TP53INP1 encodes a pro-apoptotic tumor suppressor and its antisense oligonucleotide has been used as potential treatment for castration-resistant prostate cancer." (PMID 24922517, 2014). "MiR-205 inhibits autophagy by targeting TP53INP1 in prostate cancer cells." (PMID 33402116, 2021). "TP53INP1 expression has recently been found to be enhanced in prostate cancer cells after treatment with the pro-inflammatory mediators tumor necrosis factor α and interleukin 6, indicating that TP53INP1 overexpression could be involved in inflammation-mediated prostatic carcinogenesis." (PMID 23717325, 2013). "Prostate cancer cell-derived microvesicles contain miR-155 that, when taken up by recipient fibroblasts, promotes a CAF-like phenotype via down-regulation of TP53INP1." (PMID 32957712, 2020). "However, enhancing levels of MIR30A and MIR205 downregulate the level of TP53INP1 via binding to its 3′-UTR to suppress autophagy, resulting in an increased radio-sensitivity of prostate cancer cells." (PMID 35317831, 2022).
liver cancer (7 papers, 2015 to 2023). An epithelial or non-epithelial malignant neoplasm that arises from the liver. "TP53INP1 is also targeted by miR-155, a likely oncomiR, in esophageal squamous cell carcinoma and liver cancer stem cells." (PMID 26367773, 2015).
endometrial carcinoma (6 papers, 2011 to 2025). A malignant tumor arising from the epithelium that lines the cavity of the uterine body. "These figures show that TP53INP1 exhibits lower expression in endometrial cancer samples compared to normal endometrial tissues, and that its correlation with hsa-miR-182 is significantly negative (R = −0.72) in stage IV of the disease." (PMID 40508024, 2025). "MiR-125b promotes proliferation and migration of type II endometrial carcinoma cells and tumor metastasis in patients with non-small-cell lung cancer, by targeting the tumor suppressor TP53INP1." (PMID 37958999, 2023). "This approach would allow us to assess whether such inhibition results in an increase in TP53INP1 expression, and whether it impacts the onset and/or progression of endometrial cancer." (PMID 40508024, 2025). "Our findings were, to some extent, in line with recent study which showed that miR-125b could promote proliferation and migration of type II endometrial carcinoma cells through targeting TP53INP1." (PMID 26388699, 2015).
Insulin resistance (6 papers, 2015 to 2025). Increased resistance towards insulin, that is, diminished effectiveness of insulin in reducing blood glucose levels. "Tumor protein 53‐induced nuclear protein 1 (TP53INP1) deficiency leads to oxidative stress‐associated obesity and insulin resistance." (PMID 31124296, 2019). "We used TP53INP1-deficient mice to assess in vivo the effect of a high-fat diet which favors obesity, insulin resistance and T2D, and we investigated the cellular metabolic defects induced by TP53INP1 deficiency." (PMID 25828351, 2015). "This may help us understand the mechanisms behind the association of TP53INP1 with a higher risk of diabetes from the perspective of glucose metabolism and insulin resistance." (PMID 39199149, 2024). "As obesity is generally associated with insulin resistance (IR), we investigated the susceptibility of HFD-fed TP53INP1-deficient mice to develop IR, glucose intolerance and hyperinsulinemia." (PMID 25828351, 2015). "Among the 10 most upregulated genes in NAFLD were genes related to insulin resistance (PRKCE), glucose metabolism and steatosis (PLIN1), glucose uptake regulation (ISM1), oxidative cell stress response (TP53INP1), and a proinflammatory marker (SERPINE 1)." (PMID 40489530, 2025). "In this work, we show that mice lacking TP53INP1 are prone to redox-driven obesity and insulin resistance." (PMID 25828351, 2015).
MALT lymphoma (6 papers, 2012 to 2023). An indolent, extranodal type of non-Hodgkin lymphoma composed of small B-lymphocytes (centrocyte-like cells). "This indicates that, ultimately, the upregulation of miR-142 found in MALT lymphomas likely prevents cell death by repressing TP53INP1 function." (PMID 38201290, 2023). "miR-142 was also shown to target the 3′UTR of TP53INP1 mRNA in vitro, and TP53INP1 protein levels were also lower in both H. heilmannii-infected mice and MALT lymphoma patients." (PMID 38201290, 2023). "Thus TP53INP1 staining was markedly reduced in MALT lymphoma lesions." (PMID 23209550, 2012). "TP53INP1 staining is negative or faint in the MALT lymphoma lesion, whereas normal gastric glands around the MALT lymphoma show sufficient staining for TP53INP1." (PMID 23209550, 2012). "The strong inhibition of TP53INP1 production found in GML-developing mice again suggest that it could participate in the inhibition of cell apoptosis, thereby allowing acceleration of MALT lymphoma cell proliferation." (PMID 28560185, 2017).